RAB10 (RAB10, member RAS oncogene family)
Diseases named in the same sentence as RAB10 in open-access papers (continued):
Sharing a sentence is not in itself a finding about the gene and the disease.
tumor (24 papers, 2015 to 2025). "RAB10 participates in membrane transport, substance metabolism, and is associated with tumor occurrence and development." (PMID 40842984, 2025). "For instance, RAB7 is involved in the membrane fusion of late endosomes with lysosomes and protein transport to lysosomes; RAB10 participates in membrane transport, substance metabolism, and is associated with tumor occurrence and development." (PMID 40842984, 2025). "Multifactorial analysis using the COX regression model indicated that PTNM stage, tumor subtype, and RAB10 status were risk factors for RFS and OS." (PMID 37709911, 2023). "One-way chi-square tests indicated that RAB10 expression was associated with the tumor grade (p = 0.001), molecular staging (p = 0.033), and HER2 status (p = 0.034) of BC patients." (PMID 37709911, 2023). "This is consistent with the finding that Rab10 is a downstream gene of miR-378a-3p and is associated with tumor growth." (PMID 35482482, 2022). "Another upstream regulator of Axl is RAB10, which is associated with increased tumor size and advanced tumor staging in HCC patients." (PMID 30567378, 2018). "The overexpression of RAB10 increased tumor growth and was associated with poor prognosis in HCC." (PMID 39199296, 2024). "Additionally, low expression of miR-557 and high expression of RAB10 in HCC tissues was closely associated with tumor size, degree of differentiation, TNM stage and poor prognosis in HCC patients." (PMID 38364252, 2024). "Our findings suggest that elevated expression of RAB10 in BC suggests a poor prognosis for BC, and that its ability to promote BC cell proliferation, migration and invasion in vitro is associated with tumor immune infiltrating cells in BC and is a potential biomarker or molecular target for BC." (PMID 37709911, 2023). "The expression level of RAB10 in HCC cell nucleus was significantly associated with the tumor size (P = 0.019), pathological grading (P = 0.003) and TNM stage (P = 0.027), while in paracarcinomatous cell nucleus, RAB10 was significantly associated with the pathological grading (P = 0.043)." (PMID 28460436, 2017). "Research has displayed that RAB10 plays a considerable role in tumor progression as a cancer oncogene." (PMID 38364252, 2024). "Activation of insulin signalling, inhibition of TGF‐β signalling, or modulation of ECM levels via SPARC, Rab10 or Collagen IV in the fat body, is able to rescue tissue wasting in the presence of tumour." (PMID 38014610, 2023). "We found that Rab10 protein levels was indeed elevated in the fat body of tumour bearing animals (Fig EV4K–M)." (PMID 38014610, 2023). "The analysis of the transposon integration sites identified several candidate genes, of which Man1a1, Pkp4, Rab10, Rasa1, Trps1, Vps26a, Xpnpep3 and Znf326 accelerated tumor growth, whereas the silencing of R3hcc1l reduced tumor growth." (PMID 36497409, 2022). "We evaluated the association between RAB10 expression and clinicopathological characteristics of HCC patients, including age, gender, tumor size, pathological grading and TNM stage." (PMID 28460436, 2017). "RAB10 shRNA treatment significantly reduced tumor size and weight compared with the control treatment." (PMID 28460436, 2017). "Our global transcriptome analysis further points to a tumor-promoting function by RAB10 in human HCC cells." (PMID 28460436, 2017). "These include proteins involved in vesicle transport, such as Rab10, a pathway closely linked to ARL5B-mediated lysosomal trafficking, as well as ELOVL5(elovl fatty acid elongase 5), which has been implicated in tumor immunity through immunometabolic regulation." (PMID 41451209, 2025). "RAB10 is important for the proliferation of SMAD4-altered tumor cells." (PMID 37377893, 2023). "Bioinformatics techniques were employed to explore the correlation between RAB10 and BC tumor immune cell infiltration, and to speculate the biological function of RAB10 in BC and related signaling pathways." (PMID 37709911, 2023).
tumor (continued). "Spearman correlation analysis supported these associations, showing positive correlations between risk scores and tumor stage, grade, invasion percentage, and expression of RAB10, PRKAA2, and LMO3, and negative correlations with BMI, survival time, and LMLN expression." (PMID 40804485, 2025). "In this study, miR-557 was found to have significantly low expression in HCC tissues and cells, miR-557 expression negatively with tumor size, AJCC tumor staging, and RAB10 expression while positively correlation with degree of differentiation of HCC." (PMID 38364252, 2024). "Univariate analysis using the COX regression model indicated that tumor grading, TNM stage, T stage, molecular subtype, and RAB10 status were factors affecting RFS, while TNM stage, T stage, molecular subtype, and RAB10 status were factors affecting OS." (PMID 37709911, 2023). "Modulating SPARC, a collagen binding protein or Rab10, a regulator of basement membrane fibril formation (Isabella & Horne‐Badovinac, 2016) can ameliorate ECM accumulation in the fat body in tumour bearing animals, and in turn improve muscle integrity." (PMID 38014610, 2023). "Among them, three genes (RAB10, TCOF1, and PSMD14) were found to be significantly upregulated in tumor samples, and univariate Cox regression showed that they were also significantly associated with overall survival." (PMID 36171884, 2022). "Notably, miR-181b-5p and miR-877-5p acted as negative regulators of tumor-suppressor genes (e.g., HEY2, MCL2, HAND2), while miR-204-5p and miR-143-3p appeared to indirectly target oncogenes (e.g., RAB10, DR1, PTBP3, NCBP1)." (PMID 41009685, 2025). "We confirmed these results via Western blotting analysis of tumor cells expressing AFAP1-AS1 siRNA, and found that RhoA, Rac2, Rab10, Rab11a, Rhogdi and Pfn1 were significantly upregulated, but RhoC, Rab11b and Lasp1 were significantly downregulated in NPC cell lines." (PMID 26246469, 2015).
infection (22 papers, 2015 to 2025). The state of being infected such as from the introduction of a foreign agent such as serum, vaccine, antigenic substance or organism. "Here, we found that infection-associated regulation of Rab10 dynamics involves ubiquitin signaling cascades mediated by the SidE and SidC families of Legionella ubiquitin ligases." (PMID 38771316, 2024). "In different models, the LRRK2 substrate Rab10 has been implicated in immune functions related to both infection and PD." (PMID 38862989, 2024). "Consistent with our findings in non-infected cells, complementation of the ΔsopD mutant with WT SopD expressed by bacteria on a low copy plasmid was sufficient to induce loss of Rab10 localization to tubules during infection." (PMID 34349110, 2021). "Infection of cells with a ΔsidCΔsdcA strain as well as with a strain lacking all the SidC-family proteins (ΔsidCΔsdcAΔsdcB) still caused both mono- and polyubiquitination of Rab10 but with reduced levels." (PMID 38771316, 2024). "Rab10-associated tubulation occurs early in infection may serve as a biomarker for the earliest changes in the establishment of pre-AC that can be monitored by immunofluorescence." (PMID 39866842, 2024). "Taken together, we found that Rab10 localization is finely regulated during infection; the interplay of bacterial enzymes leads to sustained association of Rab10 with the LCV and eventually dissociates it from the LCV presumably in accordance with the process of the LCV biogenesis." (PMID 38771316, 2024). "Upon infection of Caenorhabditis elegans with Pseudomonas aeruginosa, an increase in RAB-10 activity was observed in the intestine." (PMID 39087719, 2025). "As the infection progressed (48 hpi), the mature AC was finally established by the accumulation of pM74 in the outer AC of 36.85 ± 2.2% of cells surrounding Rab10 TM accumulation of the inner AC of 56.6 ± 2.9% of cells." (PMID 40868860, 2025). "They found that decreased expression of miR-378d in macrophages during infection led to upregulation of Rab10 through activation of the NF-κB signaling pathway and induction of proinflammatory cytokines." (PMID 40304865, 2025). "Results demonstrated a progressive elevation in Rab10 mRNA expression in shrimp as the infection progressed." (PMID 40001579, 2025). "The ΔsidCΔsdcA LCV also exhibited a reduced the level of Rab10 localization at 1 hr after infection." (PMID 38771316, 2024). "At 4 hr after infection with L. pneumophila strains expressing 3xFLAG-SdcB, the level of Rab10-positive LCVs was significantly higher in the cells expressing the catalytic mutant of MavC compared with those expressing wild-type MavC." (PMID 38771316, 2024). "SdcB, the previously uncharacterized SidC-family effector, resides on the vacuole and contributes to retention of Rab10 at the late stages of infection." (PMID 38771316, 2024). "The level of Rab10-positive LCVs was significantly higher with expression of wild-type SdcB than that of the catalytic mutant, suggesting that the Ub ligation activity of SdcB supports retention of Rab10 on the LCV until late stages of infection." (PMID 38771316, 2024). "At 9 hr after infection with the wild-type strain, the level of Rab10-positive LCVs was reduced to about 20% of the total LCVs (compare with that of 1–7 hr infection (~40%))." (PMID 38771316, 2024). "As the levels of the Rab10-positive LCVs were not significantly altered up to 7 hr after infection with the wild-type L. pneumophila strain, we examined Rab10 localization at a later time point after infection." (PMID 38771316, 2024). "At 7 hr post infection, Rab10 localization was readily detected on ΔsidCΔsdcAΔsdcB LCVs containing wild-type SdcB, but not the inactive SdcBC57A mutant." (PMID 38771316, 2024). "In the future, it will be interesting to examine if IAM-dependent membrane delivery represents a mechanism that cooperates with the RAB10+ membrane reservoirs and exocyst delivery to contribute to early infection events." (PMID 38600106, 2024).
infection (continued). "Here, we demonstrate that RAB10+ tubular structures exist prior to infection and serve as membrane reservoirs that are mobilized upon STm infection." (PMID 38600106, 2024). "The polyubiquitination of Rab10 was significantly observed until 7 hr after infection, although the level was slightly reduced." (PMID 38771316, 2024). "Infection with the ΔsidEs strain drastically reduced the level of Rab10-positive LCVs at all time points examined." (PMID 38771316, 2024). "Here we show that EHBP1 and MICAL-L1 impact Rab10+ tubule regulation during infection and inhibit plasma membrane scission during infection by ΔsopD mutant bacteria." (PMID 34349110, 2021). "Together, our study uncovers an important role for Rab10 in regulating plasma membrane scission and identifies the mechanism used by a bacterial pathogen to manipulate this function during infection." (PMID 34349110, 2021). "The mechanism by which Rab10 restricts plasma membrane scission during infection by ΔsopD mutant bacteria remains an important question." (PMID 34349110, 2021). "The Rab10 accumulation increased in size with the progression of infection, and at 14 hpi, 72.1 ± 3.6% of IE1+ cells expressed Rab10 in the i-preAC." (PMID 34575026, 2021). "Collectively, our findings indicate that SopD GAP activity is required to disrupt Rab10 localization to tubules during infection." (PMID 34349110, 2021). "Under conditions when plasma membrane scission was impaired (by infection by ΔsopB or ΔsopD mutant bacteria), we observed Rab10 retention at invasion sites." (PMID 34349110, 2021). "Although the accumulation of Rab10 was significantly inhibited in siArf3- and siArf4-transfected cells at 16 hpi, the establishment of infection as monitored by the nuclear expression of the IE1 protein was not impaired." (PMID 34440611, 2021). "A double mutant lacking both effectors (ΔsopBΔsopD) had the greatest impairment in Rab10 localization kinetics compared to WT infection, displaying significant enrichment of Rab10 on nascent SCVs up to 60 min p.i.." (PMID 34349110, 2021). "Next, we examined the role of Rab10 effectors in limiting plasma membrane scission during infection by ΔsopD mutant bacteria." (PMID 34349110, 2021). "In broth grown bacteria, the expression pattern of Lem27 and SidC is similar, both are induced at the post-exponential phase (Luo and Isberg, 2004), suggesting that the dynamic ubiquitination of Rab10 on the LCV occurs from the beginning of the infection." (PMID 33136002, 2020). "In contrast, the co-immunoprecipitation of SidM and LidA with Rab10 supports the result that Rab10 is a genuine target of both effectors during infection." (PMID 26755725, 2016). "To validate the interaction of SidM and LidA with the identified Rab GTPases during infection, we performed co-immunoprecipitations of the effectors with Rab2A, Rab5C, and Rab10." (PMID 26755725, 2016). "Taken together, this strengthens the conclusion that Rab10 is targeted by both SidM and LidA during infection and reflects the Rab GTPase enrichment ranking obtained from SidM interactomes." (PMID 26755725, 2016). "Our results indicated that rab-10(ycx126) animals had a comparable decline in survival rate to that of rab-10(ok1494) mutants, affirming that the intestine is the predominant contributor to the infection response." (PMID 39087719, 2025). "Moreover, we ascertained that the rise in RAB-10 activity, due to infection, was attributed to the augmented expression of LET-413/Erbin, and the nuclear receptor NHR-25/NR5A1/2 was determined to be indispensable for this increase." (PMID 39087719, 2025). "Thus, Rab10-PD is a subset of EE-derived tubular domains that are expanded in the E phase of infection and contribute to the formation of the inner part of the AC, which is fully developed in the L phase of infection." (PMID 39866842, 2024).
infection (continued). "Infection with the wild type virus, expressing m138 protein with Fc-binding properties, resulted in indistinguishable reorganization of the membrane system in the E phase of infection, including dislocation of the Golgi and perinuclear accumulation or Rab10." (PMID 39866842, 2024). "This study aims to investigate whether Rab10-positive domain (Rab10-PD) is expanded during the E phase of infection." (PMID 39866842, 2024). "Rab8A and Rab10 have yet to be studied in the context of SopD2 during infection." (PMID 38673776, 2024). "The Rab10-positive domain (Rab10-PD) in the inner pre-AC of MCMV-infected cells may be co-opted by the infection for the needs of the CMV replication cycle and could be a biomarker for pre-AC biogenesis." (PMID 39866842, 2024). "Since exocyst subunits were identified in our RAB10 BioID analysis, we hypothesized that RAB10+ membrane reservoirs might contain exocyst subunits prior to infection." (PMID 38600106, 2024). "However, during infection, these tubules displayed a trend of disassembly that was concomitant with rapid delivery of RAB10 to STm invasion sites." (PMID 38600106, 2024). "In the early stage of infection, Rab10 is recruited and retained to the LCV." (PMID 38771316, 2024). "Thus, the Rab10 effectors MICAL-L1 and EHBP1 impact Rab10+ tubules during infection by ΔsopD mutant bacteria." (PMID 34349110, 2021). "We examined the localization of Rab10 to these bacteria during infection." (PMID 34349110, 2021). "Furthermore, we show that Rab10 inhibition by SopD contributes to plasma membrane scission and bacterial internalization into SCVs during infection of host cells." (PMID 34349110, 2021). "Indeed, we show that SopD, but not SopD2, is sufficient to disrupt Rab10+ tubule localization in transfected cells and during infection." (PMID 34349110, 2021). "Thus, SopD localized to sites of Rab10 recruitment early during infection, prior to the release of Rab10 from these sites at later stages of infection." (PMID 34349110, 2021). "During infection, Rab10 and its effectors MICAL-L1 and EHBP1 are recruited to invasion sites." (PMID 34349110, 2021). "Importantly, infection with strain ∆sidC∆sdcA(pSidC+pLem27), which coexpresses Lem27 led to a clear reduction in ubiquitinated Rab10 (lanes 3 and 4)." (PMID 33136002, 2020). "Rab10 is a member of Ras oncogene family, which plays a role in pathogen infection." (PMID 32257967, 2020). "Importantly, the data suggests that ubiquitin, annexin A1, annexin A2, MavP are putative novel interaction partners and that Rab1A, Rab1B, Rab6, and Rab10 are the predominant Rab GTPases targeted by SidM during infection." (PMID 26755725, 2016). "Rab1 is upregulated in the kidney of red drum in response to intracellular bacteria Edwardsiella tarda during 4- to 24-h time periods of infection, and Rab-1A, Rab-6A, and Rab-10 proteins have been upregulated persistently in the liver of gilthead sea bream profile after confinement exposures." (PMID 25563603, 2015). "However, the survival rate of animals infected with P. aeruginosa was not evidently impacted by the absence of AMPH-1, suggesting that the decrease in infection response caused by RAB-10 deficiency is not due to impaired recycling transport." (PMID 39087719, 2025). "Likewise, a protein expression analysis revealed an increase in Rab10 levels during infection." (PMID 40001579, 2025). "Of note, a plethora of research has demonstrated the significant role of RAB-10 during the recycling transport, which brings to light that the impairment of basolateral recycling could be a contributing factor to the infection response defects." (PMID 39087719, 2025). "In MCMV-infected cells, Rab10 accumulates in the pericentriolar area very early in infection (6-7 hpi in 3T3 fibroblasts) and Rab10-PD expands into the larger perinuclear region that concentrates EE membranes as the E phase of infection progresses from 6 to 16 hpi." (PMID 39866842, 2024).